ZBED1 (zinc finger BED-type containing 1)
Description:
Functions as an E3-type small ubiquitin-like modifier (SUMO) ligase which sumoylates CHD3/Mi2-alpha, causing its release from DNA. This results in suppression of CHD3/Mi2-alpha transcription repression, increased recruitment of RNA polymerase II to gene promoters and positive regulation of transcription including H1-5 and ribosomal proteins such as: RPS6, RPL10A, and RPL12. The resulting increased transcriptional activity drives cell proliferation. Binds to 5'-TGTCG[CT]GA[CT]A-3' consensus sequences in gene promoters of ribosomal proteins. (Microbial infection) Binds to human adenovirus gene promoters and contributes to transcriptional repression and virus growth inhibition during early stages of infection.
Synonyms: ALTE; DREF; hDREF; KIAA0785; TRAMP
Tractability: PROTAC: UniProt records ubiquitination sites on it; ubiquitination databases record sites on it; its protein half-life has been measured.
Gene: Protein-coding gene on chromosome X (2,486,414 to 2,502,862, reverse strand). Ensembl gene ENSG00000214717.
Subcellular location: Nucleus, PML body; Nucleus
Subcellular location (Human Protein Atlas): Centrosome; Nucleoplasm; Nuclear membrane
Pathways (Reactome):
Metabolism of proteins: SUMOylation of chromatin organization proteins
Gene Ontology:
Molecular function: DNA-binding transcription activator activity, RNA polymerase II-specific; identical protein binding; protein binding; RNA polymerase II cis-regulatory region sequence-specific DNA binding; sequence-specific DNA binding; sequence-specific double-stranded DNA binding; SUMO ligase activity; SUMO transferase activity; transcription coactivator activity; transcription coregulator activity; DNA-binding transcription factor activity, RNA polymerase II-specific; DNA binding; protein dimerization activity
Biological process: host-mediated suppression of viral genome replication; positive regulation of transcription by RNA polymerase II; protein autosumoylation; regulation of DNA-templated transcription; protein sumoylation; regulation of transcription by RNA polymerase II
Cellular component: nuclear membrane; nucleoplasm; nucleus; PML body; chromatin
Homologues: Orthologues: chimpanzee ZBED1 (99% identical), macaque ZBED1 (99% identical), dog ZBED1 (89% identical), pig ZBED1 (83% identical), tropical clawed frog zbed1 (78% identical), rabbit ZBED1 (71% identical). Paralogues in human: ZBED4 (22% identical), ZBED6 (19% identical).
Diseases named in the same sentence as ZBED1 in open-access papers:
ZBED1 is named in the same sentence as 6 diseases in open-access papers, as found by Europe PMC text mining. Sharing a sentence is not in itself a finding about the gene and the disease. The quoted sentences say what the papers report.
gastric cancer (4 papers, 2022 to 2025). A primary or metastatic malignant neoplasm involving the stomach. "The study shows that ectopic expression of ZBED1 significantly promoted cell proliferation and colony formation abilities of the gastric cancer cell lines, which was linked to a poor prognosis." (PMID 35052473, 2022). "ZBED1 correlates with cell proliferation, with elevated expression promotes cell proliferation and apoptosis in gastric cancer." (PMID 40909263, 2025). "Studies have shown that ZBED1 is highly expressed in gastric cancer, and higher ZBED1 levels predict poor outcomes." (PMID 36588537, 2022). "Increased expression of ZBED1 in gastric cancer tissues leads to proliferation and apoptosis of tumor cells." (PMID 35832866, 2022). "Additionally, a recent study has demonstrated that ZBED1 is overexpressed in gastric cancer tissues." (PMID 35052473, 2022). "In addition, a recent study has elucidated a link between ZBED1 overexpression in gastric cancer and poor prognosis and further demonstrated that ectopic expression of ZBED1 promotes cell proliferation and colony formation abilities of gastric cancer cell lines." (PMID 35052473, 2022).
chronic tic disorder (1 paper, 2018). A neurological disorder presenting in childhood that is characterized by either motor or phonic tics, but not both, that occur daily or nearly daily for at least a year and are not attributed to an identifiable cause. "Both ZBED1 and PPP2R3B may have a role in the regulation of cell growth and division, and AKAP17A has been associated with chronic tic disorder." (PMID 30213969, 2018).
myeloma (1 paper, 2022). "In agreement with the gene model, compared with bortezomib-sensitive myeloma cell lines (negative control), there was an increase in mRNA expression of SCN9A, RGS7, NTF3, HSPB8, and ZBED1 and a decrease in CCND1, COBLL1, EGR1, OCLN, and ZBED1 mRNA expression of bortezomib-resistant cell lines." (PMID 36467498, 2022).
cancer (3 papers, 2018 to 2022). A tumor composed of atypical neoplastic, often pleomorphic cells that invade other tissues. "As ZBED1 might be involved in regulating immune responses, and especially in promoting immunosuppressive functions at the fetal-maternal interface and might be linked to proliferation and apoptosis, it would be interesting to further investigate the role of ZBED1 in cancer-related settings." (PMID 35052473, 2022). "In agreement with this, the Ki-67 labelling index of cancers did not correlate with fractions of ZBED1-positive cells." (PMID 30304065, 2018).
tumor (3 papers, 2018 to 2024). "Therefore, we examined the expression of ZBED1 in a panel of different tumor samples to investigate changes in ZBED1 expression associated with carcinogenesis." (PMID 30304065, 2018). "The Drosophila orthologue of ZBED1 has been suggested to play a role in tumorigenesis by regulating tumor suppressors and oncogenes." (PMID 30304065, 2018).
ZBED1 also shares sentences with these, for which no sentence is quoted: viral infection (1 paper).